PPP1R12C (protein phosphatase 1 regulatory subunit 12C)
Description:
Regulates myosin phosphatase activity.
Synonyms: LENG3; MBS85; DKFZP434D0412; p84; p85; AAVS1
Tractability: PROTAC: ubiquitination databases record sites on it; its protein half-life has been measured.
Gene: Protein-coding gene on chromosome 19 (55,090,913 to 55,117,639, reverse strand). Ensembl gene ENSG00000125503.
Subcellular location: Cytoplasm; Cytoplasm, cytoskeleton, stress fiber
Gene Ontology:
Molecular function: protein binding; enzyme inhibitor activity; myosin phosphatase regulator activity; phosphatase regulator activity; protein kinase binding
Biological process: neuron projection morphogenesis; signal transduction
Cellular component: cytoplasm; stress fiber
Genetic constraint (gnomAD): Loss-of-function variants: 48 observed, 78.9 expected, observed/expected ratio (o/e) 0.61, 90% interval 0.48 to 0.77. The upper end of that interval is the gene's LOEUF score, 0.77, which puts it in group 3 of 6, group 1 being the genes least tolerant of losing a copy. Missense variants: 1,057 observed, 954.99 expected, observed/expected ratio (o/e) 1.11, 90% interval 1.05 to 1.16. Synonymous variants: 480 observed, 405.9 expected, observed/expected ratio (o/e) 1.18, 90% interval 1.1 to 1.27.
Homologues: Orthologues: chimpanzee PPP1R12C (97% identical), macaque PPP1R12C (97% identical), dog PPP1R12C (90% identical), rat Ppp1r12c (88% identical), mouse Ppp1r12c (87% identical), pig PPP1R12C (84% identical), guinea pig PPP1R12C (82% identical), tropical clawed frog ppp1r12c (55% identical), zebrafish ppp1r12c (42% identical). Paralogues in human: PPP1R12A (45% identical), PPP1R12B (40% identical), PPP1R27 (8% identical).
Diseases named in the same sentence as PPP1R12C in open-access papers:
PPP1R12C is named in the same sentence as 27 diseases in open-access papers, as found by Europe PMC text mining. Sharing a sentence is not in itself a finding about the gene and the disease. The quoted sentences say what the papers report.
viral infection (4 papers, 2014 to 2025). "For example, actin cytoskeleton disturbance caused by viral infection has been reported to trigger relocalization of the the PPP1R12C protein, thereby enhancing RLR response." (PMID 39668245, 2025). "In particular, PPP1R12C is noteworthy in the context of viral infections, including those caused by RNA viruses like SARS-CoV-2, influenza, Zika virus, or vesicular stomatitis virus." (PMID 39772267, 2024). "However, in the absence of helper virus infection, AAV2 establishes latency by integrating its genome site specifically into PPP1R12C, a gene located on chromosome 19." (PMID 24829354, 2014).
adenomyosis (1 paper, 2021). The growth of endometrial tissue inside the muscular wall of the uterine corpus. "In the present study, the low expression levels of PPP1R12C and PPP1R12B were partly related to the myometrium injury in adenomyosis, and anti-NGF therapy might be advantageous for repair of myometrial defect." (PMID 32676925, 2021).
adenovirus infection (1 paper, 2014). "A potential link between downregulation of expression from the AAV2 integration target site promoter and Rep expression was further supported by a time course experiment of AAV2 and adenovirus infection in 293T cells, for which PPP1R12C and Rep expression levels were determined by real-time qRT-PCR." (PMID 24829354, 2014).
HCMV infection (1 paper, 2024). "Our findings indicate that HCMV infection disrupts PP1 function through the temporal dysregulation of at least nine recognized regulatory subunits, PPP1R10, PPP1R7, YLPM1, PPP1R11, PPP1R9A, PPP1R8 (NIPP1), PPP1R9B, PPP1R12C, and URI1." (PMID 39772267, 2024).
infection (8 papers, 2014 to 2024). The state of being infected such as from the introduction of a foreign agent such as serum, vaccine, antigenic substance or organism. "The observed infection-induced PPP1R12C repression appears to be different in 293T and HeLa cells in that the observed repression can be seen in 293T cells infected with AAV2 at high MOIs, a condition under which Rep transcripts cannot be detected by Northern blotting." (PMID 24829354, 2014). "Under permissive conditions, AAV2 infection leads to downregulation of PPP1R12C expression." (PMID 24829354, 2014). "Twenty-four hours after infection, we could observe a modest decrease in relative PPP1R12C expression levels in cells coinfected at a high MOI (left), which became more pronounced at later time points (left)." (PMID 24829354, 2014).
PPP1R12C also shares sentences with these, for which no sentence is quoted: tumor (6 papers); cancer (5); cervix carcinoma (3); osteosarcoma (2); beta thalassemia (1); breast carcinoma (1); colon carcinoma (1); Duchenne muscular dystrophy (1); Fanconi anemia (1); genetic diseases (1); glioblastoma (1); myeloid tumor (1); neuroblastoma (1); neurodevelopmental disorder (1); neurological diseases (1); Obesity (1); pulmonary alveolar proteinosis (1); Sickle Cell Anemia (1); teratoma (1); thrombocytopenia 1 (1); Wiskott-Aldrich syndrome (1); X-linked severe combined immunodeficiency (1).